NLRP3 (NLR family pyrin domain containing 3)
Diseases named in the same sentence as NLRP3 in open-access papers (continued):
Sharing a sentence is not in itself a finding about the gene and the disease.
kidney diseases (continued). "An in-depth study of the inflammasomes showed that the dysregulation of NLRP3 inflammasomes activation is closely related to various kidney diseases, including chronic glomerulonephritis, IgAN, and LN." (PMID 36874000, 2023). "This study also showed that the NLRP3 mRNA level was increased in human fibrotic renal disease and positively correlated with serum creatinine levels." (PMID 37685978, 2023). "As a new target for prevention of podocyte injury, the NLRP3 inflammasome is of great significance for prevention and treatment of kidney disease." (PMID 35656447, 2022). "After the cells are stressed, various organelles in the cell become dysfunctional and participate in the NLRP3 inflammasome activation process, thereby affecting chronic the occurrence and development of kidney disease." (PMID 35382689, 2022). "Activation of NLRP3 in kidney disease exacerbates the inflammatory response and subsequent fibrosis." (PMID 35382689, 2022). "Thereby, the degree of renal function impairment, such as GFR, will interfere with the observed NLRP3 regulation in a given kidney disease, and needs to be accounted for in the analyses." (PMID 35204131, 2022). "Accumulating studies have shown that the NLRP3 inflammasome participates in a variety of kidney diseases, including IgAN." (PMID 36676706, 2022). "The NLRP3 inflammasome is an important defensive component of the body's innate immune and stress system, and its role in kidney disease has also attracted much attention in recent years." (PMID 35382689, 2022). "According to recent studies, the NLRP3 inflammasome plays an important role in the inflammatory response of kidney disease." (PMID 35996380, 2022). "“Autophagy,” “acetylation,” and “NLRP3 inflammasome” have received much attention in the field of kidney disease as emerging research trends." (PMID 36052119, 2022). "Further studies on the pathways both upstream and downstream of the NLRP3 inflammasome will provide new therapeutic targets for multiple kidney diseases." (PMID 35656447, 2022). "Autophagy and NLRP3 inflammasome are emerging research trends that have gradually attracted the interest of researchers, especially regarding kidney diseases." (PMID 36052119, 2022). "Activated NLRP3 inflammasome is involved in the pathogenesis of many kidney diseases, such as acute kidney damage, calcium oxalate crystal nephropathy, and CKD." (PMID 35223948, 2022). "Some researchers have reported that in kidney disease models, such as unilateral ureteral‐obstructed mice and chemical reperfusion‐injured mice, NLRP3 expression was augmented." (PMID 33783986, 2021). "Overall, studies have illustrated the decreased expression of IL-1β, IL-18, α-SMA, collagen I and other fibrosis-related indicators in NLRP3−/− mouse models of nephropathy, suggesting that NLRP3 participates in renal inflammation and fibrosis." (PMID 34944017, 2021). "The occurrence and progression of kidney diseases are more or less related to pyroptosis, and the inflammatory body NLRP3 is the most well-studied." (PMID 34007404, 2021). "It is important to emphasize that NLRP3 inflammasome seems to have complex effects in kidney disease and LN establishment." (PMID 34830358, 2021). "In this review, the interplay between autophagy and the NLRP3 inflammasome and the mechanisms in renal diseases are explored to provide ideas for relevant basic research in the future." (PMID 34884572, 2021). "It has been reported that the interplay between autophagy and NLRP3 inflammasome is involved in many diseases, including renal diseases." (PMID 34884572, 2021). "Up to now, most investigations on the role of NLRP3 inflammasome in kidney diseases have been conducted either in animal models or in cultured cells, however, the data collected from humans are infrequent." (PMID 34904012, 2021).
kidney diseases (continued). "Other kidney diseases such as diabetic nephropathy, obstructive nephropathy, and crystal nephropathy can also activate the inflammasome NLRP3, induce inflammation, and lead to a progressive glomerular and/or tubulointerstitial fibrosis." (PMID 34830358, 2021). "Many kidney diseases exhibited increased expression of NLRP3 mRNA in kidney tissue from human renal biopsies, and the NLRP3 mRNA level was correlated with renal function." (PMID 33912556, 2021). "Deficiency of NLRP3, ASC or caspase-1 in mice with nephropathy induced by deposits of calcium oxalate in the renal tubules abrogates the inflammation and loss of renal function." (PMID 34829842, 2021). "The inflammasome-dependent NLRP3 mediates the progression of kidney diseases by escalating local kidney inflammatory response and promoting a crosstalk between the immune cells and the nonimmune renal cells." (PMID 34381495, 2021). "The activation of NLRP3 inflammasome plays a complex and important role in promoting the occurrence and development of renal disease." (PMID 34305953, 2021). "Another group demonstrated that P2X4 and NLRP3 were highly expressed and these two proteins co-localized in renal tubule cells of type 2 diabetic patients with nephropathy." (PMID 33897694, 2021). "At present, there have been many studies on the negative regulation of NLRP3 inflammasome by autophagy in renal diseases, but the reports of NLRP3 inflammasome regulating autophagy are rare." (PMID 34884572, 2021). "Within the studies concerning pyroptosis in the field of kidney diseases, several have focused on proteins related to the pyroptosis signaling pathway, that is, NLRP3, caspase-1, and the inhibitor or activator of GSDMD." (PMID 34007404, 2021). "Nevertheless, exacerbated NLRP3 inflammasome activation is involved in the pathogenesis of many diseases such as Alzheimer’s, rheumatoid arthritis, renal diseases and tumors, all of which are characterized by significant chronic inflammation." (PMID 34829842, 2021). "Although these other pathways seem to influence inflammatory processes, the NLRP3 inflammasome, IL-1β, and IL-18 levels are still the main targets used to identify potential molecules inhibitors in LN and kidney diseases." (PMID 34830358, 2021). "It is believed that through further research in the future, targeting autophagy/NLRP3 inflammatory bodies will become a new strategy for the treatment of renal diseases." (PMID 34884572, 2021). "At present, the existing research has revealed that autophagy suppresses NLRP3 inflammasome by scavenging mtROS, so as to improve renal disease." (PMID 34884572, 2021). "The important role of the NLRP3 inflammasome in renal inflammation has been demonstrated in several renal disease models, including AKI." (PMID 32131850, 2020). "Numerous studies have confirmed that NLRP3 is the most typical inflammasome in the kidney, plays an important regulatory role in a variety of kidney diseases, and affects disease progression." (PMID 32410864, 2020). "These renal diseases can be ameliorated by NLRP3 inflammasome inhibitors or genetic deletion of inflammasome components." (PMID 33202867, 2020). "NLRP3 is known to mediate renal injury via inflammasome formation in various renal diseases, such as RIAKI, ischemic reperfusion injury (IRI), contrast-induced AKI, and unilateral ureter obstruction nephropathy." (PMID 33202867, 2020). "Hua KF confirms that ROS generation and activation of NF-κB and the NLRP3 inflammasome are crucial mechanistic events involved in the progression of the renal disorder." (PMID 33456483, 2020). "Although current studies have confirmed the relationship with NLRP3 inflammasome and kidney disease, the mechanism needs further elucidation." (PMID 32175320, 2020). "NLRP3 inflammasome has been increasingly focused due to aggravating the inflammation in diverse renal diseases." (PMID 32765277, 2020).
kidney diseases (continued). "Secondly, NLRP3 among inflammasome components is well known to various kidney disease including IR-AKI." (PMID 32414157, 2020). "In this review, we focus on the relationship between inflammasomes and kidney diseases, especially the role of the NLRP3 inflammasome in different kinds of kidney disease via both canonical and non-canonical signal pathways." (PMID 32175320, 2020). "NLRP3 inflammasome activation and subsequent IL-1β maturation have increasingly been reported to participate in the pathogenesis of various kidney diseases." (PMID 31616439, 2019). "Here, we will address what has been studied so far about the role of NLRP3, primarily focusing on the mechanism of action of the inflammasome-independent and inflammasome-dependent forms of NLRP3 in kidney diseases." (PMID 31694192, 2019). "This review will summarize the mechanisms by which NLRP3 functions in the kidney in both inflammasome-dependent and inflammasome-independent ways and the role of NLRP3 and NLRP3 inhibitors in kidney diseases." (PMID 31694192, 2019). "The NLRP3 inflammasome has broad implications for a variety of kidney diseases due to its connection with immunity, proinflammatory cytokines and autophagy." (PMID 31475012, 2019). "Inflammasome-dependent NLRP3 mediates the progression of kidney diseases by escalating the inflammatory response in immune cells and the cross-talk between immune cells and renal nonimmune cells." (PMID 31694192, 2019). "Our results clearly indicate that nicotine induced activation of NLRP3 inflammasomes in podocytes contributes to the development of kidney diseases." (PMID 31835256, 2019). "The genetic or pharmacological inhibition of NLRP3 ameliorated renal injuries in various animal models of kidney diseases." (PMID 31694192, 2019). "Previous studies have reported that the activation of NLRP3 inflammasome triggered the host inflammatory responds in some renal diseases." (PMID 31474993, 2019). "The expression of NLRP3 and activation of its downstream signaling proteins in glomeruli has been described by several studies for various renal diseases." (PMID 31796125, 2019). "NLRP3 activation in kidney diseases aggravates inflammation and subsequent fibrosis, and this effect is abrogated by genetic or pharmacologic deletion of NLRP3." (PMID 31694192, 2019). "In accordance with animal studies, NLRP3 mRNA was increased in human fibrotic renal diseases and positively correlated with serum creatinine levels." (PMID 31694192, 2019). "The NLRP3 inflammasome plays an important role in mediating podocyte injury in various kidney diseases." (PMID 31796125, 2019). "The Nucleotide binding and oligomerization domain-like receptorfamily pyrin domain-containing 3 (NLRP3)-inflammasome plays an important role in various diseases, including a variety of kidney diseases." (PMID 29929501, 2018). "The relocalization of NLRP3 to the mitochondria and mitochondrial ROS and mitochondrial DNA are the major secondary signals in kidney disease." (PMID 30483252, 2018). "In the past years, the pathogenic role of P2X7R and NLRP3 inflammasome in kidney diseases was highly noticed, and the expression of P2X7R and all the components of NLRP3 inflammasome in podocytes was also affirmed." (PMID 30534570, 2018). "Emerging evidence has suggested an important role for the NLRP3 inflammasome in the pathogenesis of acute and chronic injury in a wide spectrum of renal diseases including ischemic AKI21–24,36." (PMID 29500339, 2018). "In conclusion, The NLRP3 inflammasome is increasingly being recognized as an integral component of the pathogenesis of many renal diseases and their complications." (PMID 29371912, 2017). "NLRP3 expression was found to be increased in renal biopsy samples from patients with various renal diseases, with increased levels correlating with decreased renal function." (PMID 28348462, 2017).
kidney diseases (continued). "Recently, the NLRP3 inflammasome has been shown to play a pivotal role in inflammation in murine kidney disease models." (PMID 28821730, 2017). "The NLR family pyrin domain-containing 3 (NLRP3) inflammasome has been shown to play a pivotal role in inflammation in a mouse kidney disease model." (PMID 28821730, 2017). "In this extension of our prior work, we employed human nephrectomy samples, kidney disease biopsies and primary tubular epithelial cells to characterize NLRP3 in the context of the human kidney and IgAN, a common chronic human kidney disease." (PMID 27093923, 2016). "This study is the first to extensively characterize NLRP3 in the context of human kidney disease using only human biopsy tissues and primary, low passage human cells." (PMID 27093923, 2016). "Despite these observations, the cellular localization and characterization of NLRP3 in the human kidney or a temporal relationship to human kidney disease has yet to be confirmed." (PMID 27093923, 2016). "The Nlrp3 inflammasome is a crucial event in the progression of kidney disease, including unilateral ureteral obstruction (UUO), ischemia/reperfusion injury, and proteinuric animal model." (PMID 27721575, 2016). "Together, our data provide a perspective on the biology of NLRP3 in the context of human kidney disease." (PMID 27093923, 2016). "The results of the present study as well as our previous study provide new insights into the role of NLRP3 inflammasomes in kidney diseases." (PMID 26045078, 2015). "Several papers, then, indicate that danger-associated molecular patterns (DAMPs) such as extracellular ATP, ROS, extracellular matrix components, are capable to activate NLRP3 inflammasome in several renal diseases." (PMID 25798846, 2015). "The most extensively studied component of the NLRP3 inflammasome in relation to renal disease is IL-18." (PMID 24450291, 2014). "The NLRP3 inflammasome is becoming increasingly recognized as integral to the pathogenesis of many renal diseases and their complications." (PMID 24450291, 2014). "Our data also confirm that ROS generation and activation of NF-κB and the NLRP3 inflammasome are crucial mechanistic events involved in the progression of the renal disorder." (PMID 24204969, 2013). "Recent studies document the role of the NLRP3 inflammasome-caspase-1-IL-1β/IL-18 axis in kidney disease." (PMID 22701621, 2012). "NLRP3 is involved in the occurrence and development of kidney disease, whether in glomerular cells, tubular cells, interstitial cells, or infiltrating inflammatory cells." (PMID 41357229, 2025). "In renal disease, tubular epithelial cells have been identified as key targets of NLRP3 activation." (PMID 41334910, 2025). "Mechanistically, TMAO may contribute to kidney disease pathogenesis by inhibiting autophagy, activating the NLRP3 inflammasome, and inducing mitochondrial dysfunction." (PMID 40134790, 2025). "In addition to animal experiments and in vitro studies, the NLRP3 inflammasome also plays a crucial role in the occurrence and development of kidney diseases in humans." (PMID 41357229, 2025). "Therefore, studies using specific renal macrophage cell types and NLRP3 inflammasomes-related signaling protein knockout mice for kidney disease models are needed in the future." (PMID 38740765, 2024). "The activation of the NLRP3 inflammasome extends beyond immune cells such as macrophages and dendritic cells to include intrinsic renal cells, underscoring its broad involvement in renal disease pathogenesis." (PMID 39104818, 2024). "These factors may be the key to the activation of NLRP3 inflammatory bodies and the main pathological mechanism of inflammatory damage in renal disease." (PMID 39445333, 2024). "NLRP3 was involved in the onset and progression of renal diseases." (PMID 38758227, 2024). "Protein levels of SCAP, FASN, PLIN2, NLRP3, and GSDMD were higher in fibrotic human kidney tissue samples, likely indicating that DNL could be associated with kidney disease." (PMID 38051585, 2023).
kidney diseases (continued). "Interestingly, recent studies have reported that cardiac expression of NLRP3 is increased in experimental models of CKD, suggesting a potential role for the NLRP3 inflammasome in kidney disease–induced cardiac dysfunction." (PMID 37581942, 2023). "The NLRP3 inflammasome, a multiprotein complex, is involved in various renal diseases." (PMID 37261217, 2023). "These intersecting findings indicate that the NLRP3 inflammasome may play a role in the occurrence and progression of kidney diseases." (PMID 35656447, 2022). "Other studies have also shown that the renin–angiotensin–aldosterone system (RAAS) and endoplasmic reticulum stress (ERS) can regulate the NLRP3 inflammasome and play an important part in the development of renal diseases, including DN, obesity-related kidney disease and AKI." (PMID 36676706, 2022). "Thus, in the context of direct injury to renal tubular epithelial cells and fibroblasts, inflammasome-independent NLRP3 plays a key role in renal disease by regulating apoptosis, fibrosis, and the mitochondrial injury." (PMID 35719709, 2022). "Up-regulation of NLRP3 mRNA in kidney biopsy of patients with various kidney diseases (including IgA nephropathy, acute tubular necrosis, focal segmental glomerulosclerosis, lupus nephritis, minimal change disease and hypertensive nephropathy) has been confirmed." (PMID 35382689, 2022). "Interestingly, whilst the role of the NLRP3 inflammasome in kidney disease pathogenesis is irrefutable, there is a clear demand for increased studies to outline the exact nature of the pathway involved." (PMID 35755447, 2022). "Due to this property, TAEV might serve as a promising reno-protective agent in delaying the progression of CKD and ROS/ERK1/2-mediated NLRP3 signal pathway might be a vital target in treating kidney diseases." (PMID 36212965, 2022). "There is currently a lack of research on the mechanism of probiotics in the treatment of kidney disease, but a few studies have reported that probiotics, especially Bifidobacterium, could blunt the activating signal of NLRP3 in intestinal tissue." (PMID 36038927, 2022). "A full understanding of the mechanism of the inflammasome in kidney disease may help to comprehend the pathogenesis of renal disease and NLRP3, which may be a promising therapeutic target in CKD." (PMID 36359366, 2022). "NLRP3 inflammasome not only mediates the progression of renal disease by activating inflammatory responses in immune cells but also regulates the apoptosis of renal tubular epithelial cells by interacting with mitochondria and mediating the production of ROS and mitochondrial autophagy." (PMID 35795279, 2022). "New evidence in the study of the NLRP3 inflammasome may contribute to the development of renal autoimmunity in kidney disease." (PMID 35382689, 2022). "Activation of NLRP3 inflammasome contributes to the maturation and release of proinflammatory factors such as IL-1β and IL-18, which is a vital component of inflammatory response and plays an important role in the progression of kidney diseases." (PMID 36212965, 2022). "In addition, although it has been reported that NLRP3 inflammasome can negatively regulate autophagy through caspase-1, the role and mechanism of NLRP3 inflammasome inhibition of autophagy in renal diseases need to be further clarified." (PMID 34884572, 2021). "Other studies have found that RTECs express a functional NLRP3 inflammasome in renal diseases." (PMID 33783986, 2021). "NLRP3 activation in renal diseases aggravates inflammation, as well as the consequent fibrosis." (PMID 34381495, 2021). "The role of NLRP3 in inflammasomes has been studied extensively; it is an important determinant in multiple kidney diseases, including unilateral ureteral occlusion (UUO), crystal-induced renal injury, nephrocalcinosis-related chronic kidney disease and metabolic syndrome-related kidney disease." (PMID 34944017, 2021).